TNF (tumor necrosis factor)
Diseases named in the same sentence as TNF in open-access papers (continued):
Sharing a sentence is not in itself a finding about the gene and the disease.
melanoma (continued). "Further, the pro-apoptotic activity of sulforaphane on highly metastatic melanoma cells was demonstrated and associated with a significant caspases activation and down-regulation of pro-inflammatory cytokines such as TNF-α, IL-6, IL-1β, IL-12p40, and GM-CSF in murine melanoma cells." (PMID 36768978, 2023). "Regarding melanoma, in a case-control study using an administrative database, anti-TNF therapy was associated with an increased risk of melanoma, even after adjustment (OR = 1.88; 95% CI = 1.08–3.29), but not in the case of NMSC (OR = 1.14; 95% CI = 0.95–1.36)." (PMID 36765829, 2023). "Another study has emphasized that circulating B lymphocytes produce tumour necrosis factor α (TNF-α) and/or IL-6, these being associated with tumour unresponsiveness and poor survival of melanoma patients who underwent anti-cytotoxic T-lymphocyte associated protein 4 (CTLA4) antibody therapy." (PMID 35334544, 2022). "Finally, we show that the expression of melanoma-associated PP6 inactivating mutants offer resistance to TNFα." (PMID 36071040, 2022). "Since our data showed that phosphatase-inactive D84N-PP6 mutant cells were resistant to TNFα-mediated cell death, we next examined whether melanoma-associated PP6 inactivating mutations would affect TNFα-mediated cell death." (PMID 36071040, 2022). "Macrophage derived-TNF was identified as a crucial melanoma growth factor that contributed to resistance to MAPK pathway inhibitory treatments in a mouse model of BrafV600E mutated melanoma." (PMID 34439098, 2021). "However, other studies indicate that only cells with N-RAS mutation (changing Gln to Arg, which occurs in 15–20% of melanomas) constitutively express and release IL-1α, IL-6, and TNF-α into the medium." (PMID 34068679, 2021). "In murine macrophages, PTX-mediated stimulation of TLR4 not only induced the acquisition of an M1 phenotype, as indicated by the secretion of TNFα and IL-12 but was also able to counteract M2 polarization and to revert melanoma TAMs towards an M1 profile, which in turn caused melanoma regression." (PMID 34712615, 2021). "Importantly, the high content of CCL20/TNF/VEGFA is strongly associated with a worse prognosis in primary melanoma patients." (PMID 34439098, 2021). "In melanoma, anti-PD-1 therapy induced the regression of 20% of the tumors, while a synergistic antitumor effect was observed when anti-PD-1 was used in combination with anti-TNFα antibodies causing tumor regression of 75%." (PMID 32391269, 2020). "Consequently, it was demonstrated that TNFα- and cAMP-mediated signals oppositely regulate the melanoma-associated GD3 synthase gene in human melanocytes, and that regulation of the gene in melanoma cells was different from that in melanocytes." (PMID 31611597, 2019). "TNFα amplifies ceramide generation by activating two different intracellular signaling cascades involving ASMase as well as cytosolic phospholipase A2 (cPLA2) in PKCδ deficient B16F10 melanoma cells." (PMID 30701020, 2018). "Also, intra-tumoral administration of adenoviruses encoding IL-2 and TNF-α into B16 melanoma tumors showed anti-tumor activity in comparison to T-cell or control viral transfer alone." (PMID 29588627, 2018). "In melanoma patients an increased TNF gene expression is seems to be linked to αPD-1 therapy." (PMID 30647851, 2018). "It is hypothesized that melanoma exosomes induce the release of vascular endothelial cell derived tumor necrosis factor alpha (TNF-α), which causes the lymphatic endothelial cells to tolerate tumor growth within the nodes." (PMID 27941674, 2016). "Interestingly, the relationship between tumor necrosis factor alpha and ultraviolet light lends credence to the idea that sun exposure plays a central role in the development of melanoma-associated sarcoidosis." (PMID 26083934, 2015). "Similarly, a case–control study showed an increased risk of melanoma with anti-TNF treatment in IBD patients." (PMID 26450611, 2015).
melanoma (continued). "We found that MITF and c-Jun transcriptionally repress each other and therefore c-Jun induction by TNF-α instigates a feed-forward loop of melanoma dedifferentiation through MITF loss that is mechanistically linked to increased cytokine responsiveness caused by accumulation of c-Jun." (PMID 26530832, 2015). "Because the size of the CSC compartment is directly linked to a tumor burden, by enlarging this compartment, TNF may cause a predisposition to melanoma development and evolution." (PMID 25223735, 2014). "Intratumoral administration of P. acnes successfully protected the host against melanoma progression in vivo by inducing both cutaneous and systemic Th1 type cytokine expression, including TNF-α and IFN-γ, which are associated with subcutaneous granuloma formation." (PMID 22216160, 2011). "More recently, we have demonstrated upregulation of integrin expression (specifically α3, α4 and β1 integrin subunits) within 24 h of TNF-α exposure for the HBL melanoma cells associated with TNF-α stimulated increased invasion through fibronectin – an effect largely blocked by α-MSH." (PMID 12966436, 2003). "Indeed, another group of genes, including genes of the immune system, may be implicated in melanoma onset: IL-10, IL-1β, TNF-α (tumor necrosis factor alpha), HLA (human leukocyte antigen class II) genes, and IRF4 (interferon regulatory factor 4) genes." (PMID 40869905, 2025). "Furthermore, elevated levels of the proinflammatory proteins present in the “cytokine storm” linked to COVID‐19, such as TNF‐α, IL‐1α, IL‐1β, IL‐6, and ferritin, may have also caused skin depigmentation or hypopigmentation, ultimately resulting in melanoma." (PMID 40270775, 2025). "Our study highlights that ceramide metabolism alterations are causally involved in TNF-induced melanoma cell dedifferentiation and suggests that the evolution of specific ceramide metabolites in plasma may be considered as predictive biomarkers of resistance to immunotherapy." (PMID 39136013, 2024). "Furthermore, intratumoral administration of an oncolytic virus encoding TNFα and IL-2 also enhanced anti-PD-1 efficacy in mouse melanoma by improving CD8+ T-cell infiltration, suggesting that delivering high concentrations of TNFα to tumors can enhance the efficacy of immunotherapy." (PMID 38195677, 2024). "However, the risk of lymphoma and melanoma increased in patients receiving anti-TNF therapy." (PMID 36983432, 2023). "Thus, our data demonstrate that melanoma-associated PP6 mutations mediates the resistance to TNFα." (PMID 36071040, 2022). "However, the effectiveness of adoptive T cell therapies could be hindered by the TNF-α-induced reversible loss of melanoma-associated antigens, which promoted melanoma plasticity and led to the appearance of resistant, dedifferentiated cancer cells." (PMID 33171792, 2020). "Patients on TNF-α inhibitors compared to patients on conventional sDMARDs did not have a higher risk for malignancies in general, lymphoma or non melanoma skin cancer, but the risk of melanoma could be slightly increased." (PMID 25815013, 2015). "A recent study assesses how TNF-driven changes in CER metabolism influence melanoma cell dedifferentiation." (PMID 41596686, 2026). "Preclinical studies in melanoma showed that TNF inhibition attenuated T cell apoptosis and suppressed PD‐L1/TIM‐3 upregulation induced by anti‐PD‐1 therapy." (PMID 41491612, 2026). "Other cytokine trajectories, including IL-2 and TNF-α patterns, showed variability across cancer types and timepoints, but given the limited sample size, particularly in melanoma, these results remain exploratory." (PMID 41020868, 2025). "Specifically, plasma levels of IL-1α, IL-6, IL-17, and TNFα, proinflammatory cytokines, were significantly higher in the Melanoma + Combi-ICI group compared to controls." (PMID 40313772, 2025). "Melanoma patients showed sustained IL-2 and TNF-α increases, while NSCLC patients displayed heterogeneous cytokine dynamics." (PMID 41020868, 2025).
melanoma (continued). "Diacylglycerol kinase α (type I isomer) was reported in 2007 to inhibit apoptosis in human melanoma cells induced by tumor necrosis factor alpha (TNF-α) by activating nuclear factor kappa B (NF-κB)." (PMID 41149902, 2025). "To assess the impact of Siglec-7-based CSR on T cell function, we first co-cultured engineered T cells with various human melanoma cell lines and measured TNFα, IFNγ and IL-2 secretion." (PMID 40433387, 2025). "Consistent with sublethal apoptosis in immune stressed human tumors, treatment of melanoma tumor slices with anti-PD-1, IFNγ and TNF induced caspase-active yet viable tumor cells." (PMID 40166148, 2025). "The most salient observations included AP1 and AP2 gene enrichment in melanoma TNF response, AP1 gene enrichment in the Verfaillie invasive gene set and AP2 enrichment in the Hoek invasive gene set." (PMID 38183207, 2025). "The selective enrichment of ILC1s in the absence of a parallel increase in canonical effector cytokines such as IFN-γ and TNF-α suggests a state of functional decoupling as observed in other cancer types including melanoma and lung cancer." (PMID 41368637, 2025). "Melanoma patients exhibited a marginally higher overall TNF-α level compared to NSCLC patients, F (1, 70.3) = 3.81, p = 0.055." (PMID 41020868, 2025). "In the melanoma cohort, baseline cytokine correlations also pointed to shared regulatory mechanisms, particularly between TNF-α and IL-10." (PMID 41020868, 2025). "Gene therapy for patients with cancer began in earnest in the USA, starting with the first administration of tumor necrosis factor (TNF) gene-transferred tumor-infiltrating lymphocytes to patients with malignant melanoma in 1989." (PMID 40699667, 2025). "Prior studies in melanoma demonstrate that the TNF-α/NF-κB/MMP9 axis promotes early metastasis by facilitating detachment from primary tumors and systemic dissemination via vascular or lymphatic routes." (PMID 40948800, 2025). "As highlighted in this study, both NSCLC and melanoma patients exhibited complex TNF-α trajectories." (PMID 41020868, 2025). "Elevated IL‐6 and TNF‐α levels have been shown to increase PD‐L1 expression on melanoma cells and MDSCs, thereby reinforcing an immunosuppressive tumor milieu." (PMID 40926366, 2025). "The involvement of TNF-α in this process was supported by data obtained by a research group that showed that blocking the TNF-α receptors in an immunogenic mouse melanoma model under anti-PD-1 therapy induced the regression of melanoma in 75% of subjects." (PMID 40564098, 2025). "Tumor necrosis factor-α (TNF-α) is an inflammation-related regulatory protein that is increased in multiple tumor types such as melanoma, prostate cancer, or RCC." (PMID 40699758, 2025). "This supports previous reports of VEGF reduction of TNF-α-induced upregulation of ICAM-1 and VCAM-1 in cultured ECs and tumour-associated ECs isolated from melanoma tissues." (PMID 40650058, 2025). "For example, anti-TNF antibodies have been shown to enhance the efficacy of anti-PD-1 treatment in mouse models of melanoma." (PMID 40797218, 2025). "Strong inter-cytokine correlations were observed (NSCLC: TNF-α vs. IL-10, ρ = 0.60, 95% CI 0.19–0.82; melanoma: ρ = 0.93, 95% CI 0.44–0.99)." (PMID 41020868, 2025). "In consideration of the production of these cytokines and their involvement in melanoma resistance to immunotherapy, we evaluated the blood levels of the cytokines TNF-α and IL-6." (PMID 40564098, 2025). "Consistent with the canonical role of type-1 proinflammatory cytokines in controlling tumor growth, neutralization of IFN-γ and TNF-α accelerated the growth of B16ova melanoma." (PMID 40553564, 2025). "Then, these cells were co-cultured with various human melanoma cell lines and measured IFNγ, TNFα and IL-2 secretion." (PMID 40181966, 2025). "Incubating WM35 melanoma cells with TNF significantly inhibited AC enzyme activity under our experimental conditions." (PMID 39136013, 2024).
melanoma (continued). "Our previous work highlighted that TNF impairs anti-melanoma immune responses by inducing cell death of activated CD8+ T lymphocytes in a TNF Receptor 1 (TNFR1)-dependent manner." (PMID 39136013, 2024). "Previous studies showed that aggressive melanoma cells release TNF‐α, which elicits melanoma dedifferentiation, promoting immune escape and melanoma relapse." (PMID 39496484, 2024). "Herein, we evaluate the impact of ceramide metabolism changes triggered by TNF in melanoma cell dedifferentiation." (PMID 39136013, 2024). "In conclusion, ANH from MLiM showed an upregulation in CXCR4 and COL1A1/2, while melanoma cells of MLiM showed a significant upregulation in TNF." (PMID 39496484, 2024). "Targeted therapy led to high infiltration of TNFα-expressing TAMs in BRAF-mutant melanoma patients and in melanoma allografts." (PMID 38942020, 2024). "Studies indicate that KLF5 can enhance the expression of CYP1A1, which are involved in inducing the expression of proinflammatory cytokines (such as TNF) that can influence melanoma progression." (PMID 39835132, 2024). "We conducted RNA sequencing and mass spectrometry analyses to investigate TNF-induced dedifferentiation in two melanoma cell lines." (PMID 39136013, 2024). "Monocytes cocultured with CCL2-producing melanoma cells expressed TNF; monocyte-derived TNF induced tubule formation of HUVEC cells in vitro." (PMID 38786066, 2024). "Several groups have demonstrated that in murine models of melanoma and colon cancer, combining TNF blockade with ICI therapy abrogates the irAE and improves anti-cancer immune responses." (PMID 39737191, 2024). "In line with our findings, the production of TNF-α is essential for the elimination of melanoma by Th1 cells." (PMID 38920557, 2024). "Intratumoral injection of the cGAMP-loaded polymersome significantly increased the frequency of TNF-α positive CD8+ T cells compared to using free cGAMP in melanoma TME." (PMID 38185685, 2024). "Melanoma cells exhibit a considerable increase in the pro-inflammatory IL-6 gene due to TNFα/TNFR1 signaling and TNF-α overexpression." (PMID 38398617, 2024). "TNF‐α also enhances the expression of programmed cell death ligand 1 (PD‐L1) in tumour cells including melanoma." (PMID 39496484, 2024). "The role of ceramide metabolites in TNF-induced melanoma cell dedifferentiation is further documented by the inhibition of this process by eliglustat, pointing to the role of glycosphingolipids in melanoma cell dedifferentiation upon TNF treatment." (PMID 39136013, 2024). "For example, it has been shown that melanoma cells can undergo dedifferentiation when stimulated with TNFα." (PMID 39736644, 2024). "MAPK is primarily activated along the TNF branch in keratinocytes, to a lesser degree in fibroblasts, and at low activity levels in type 1 melanoma spots." (PMID 38785552, 2024). "We show that TNF-induced AC inhibition and glycosphingolipid production contributes to accumulation of ceramide metabolites and melanoma cell dedifferentiation." (PMID 39136013, 2024). "For example, serum IL-1β, IL-4, IL-6, IL-10, GM-CSF, TNF-α, and sPD-L1 has significant sex-related predictive effects on OS in patients with melanoma or non-small cell lung cancer treated with ICIs." (PMID 39085893, 2024). "Both, STAT3 and TNFα signaling have been described to drive the transition of differentiated melanoma cells toward dedifferentiation." (PMID 39398277, 2024). "Pathway analyses on all these genes showed, aside from proliferation (E2F targets, G2M checkpoint) and inflammation (TNF, interferon signaling) hallmarks, a striking enrichment in melanoma signatures." (PMID 38519642, 2024). "Among the pathways regulated by TNF signaling, sphingolipid-related biological pathways, as defined by Gene Ontology (GO), were correlated with melanoma dedifferentiation." (PMID 39136013, 2024). "Conversely, blocking de novo ceramide synthesis impaired TNF-induced melanoma cell dedifferentiation." (PMID 39136013, 2024).
melanoma (continued). "In NGDSP analysis adjacent normal hepatocytes (ANH) had higher CXCR4 and COL1A1/2 levels than distant normal hepatocytes (DNH), while melanoma cells had higher TNF‐α levels." (PMID 39496484, 2024). "TNF, produced in melanoma tumors following ICI, is involved in the resistance to anti-PD-1 antibody in mice." (PMID 39136013, 2024). "Overall, our data indicate that TNF triggers the accumulation of ceramide metabolites, including glycosphingolipids, which likely contribute to melanoma cell dedifferentiation." (PMID 39136013, 2024). "It is predicted that melanoma fail to activate the migration of LCs to lymph nodes until the tumor reaches a critical size, which is determined by a positive TNF-α feedback loop within the melanoma in silico model." (PMID 38229178, 2024). "To investigate the role of ceramide metabolism in melanoma cell dedifferentiation induced by TNF treatment, we incubated the WM35 melanoma cell line with exogenous ceramides or with an inhibitor of ceramide synthesis." (PMID 39136013, 2024). "We found that in response to TG or HA15 treatment, both the transcription and secretion of IL-6 and TNF-α were prominently increased in both A2058 and A375 melanoma cell lines." (PMID 38291473, 2024). "The present study shows that TNF-induced changes in ceramide metabolism contribute to melanoma cell dedifferentiation, a process which facilitates melanoma progression and resistance to immunotherapies." (PMID 39136013, 2024). "In the literature, a type of melanoma known as “melanoma resistant to apoptosis induced by ligand tumor necrosis factor” (TRAIL-Melanoma) has been proposed to result from the use of isolation." (PMID 39064929, 2024). "The addition of recombinant DbpA enhances melanoma cell proliferation, migration, and competes with tumor necrosis factor (TNF) binding to its receptor (TNFR1)." (PMID 39451259, 2024). "We leveraged data from the clinical trials MELANFα (NCT03348891) and TICIMEL (NCT03293784), involving 48 advanced melanoma patients treated with ICI or ICI in combination with anti-TNF (paired pre- and post-treatment samples)." (PMID 39136013, 2024). "A phase I clinical trial aims at investigating the efficacy of the expression of the tumor necrosis factor (TNF-α) in cutaneous metastases of malignant melanoma after the intratumoral jet injection of the MIDGE gene carrier." (PMID 38540320, 2024). "We focused on TFs commonly regulated between the 24 hours TNF treatment condition and AC knockdown in melanoma cells." (PMID 39136013, 2024). "On the other hand, TNF administration in the murine melanoma metastatic model increased metastasis and correlated with the infiltration of regulatory CD4(+)/Foxp3(+) T cells in the lungs." (PMID 39650654, 2024). "The polyphenols examined have shown potential as anticancer medicines targeting inflammatory cytokines since they dramatically reduce IL-6, IL-10, and TNF-α, reducing melanoma cell proliferation and migration." (PMID 38398617, 2024). "In situ immunofluorescence analysis of human primary melanoma samples indicates that there is a strong correlation between the abundance of TAMs expressing CCL20/TNF/VEGF-A and worse prognosis." (PMID 38397187, 2024). "In malignant melanoma cells, intracellular Trx/TrxR expression together with endogenous TNFα is correlated with resistance to TNFα-induced cytotoxicity." (PMID 39164783, 2024). "Among the commonly upregulated genes in tumour areas, the focus was on TNF as it is highly expressed in melanoma cells." (PMID 39496484, 2024). "Spatial transcriptomic analysis demonstrated an upregulation of the TNF signalling pathway in melanoma cells of MLiM." (PMID 39496484, 2024). "Some phase I and II trials showed disease stabilization in various malignancies, and the phase Ib trial (NCT03293784) combining TNF inhibitor certolizumab with anti-PD-1/anti-CTLA-4 in melanoma patients demonstrated safety and high response rates." (PMID 39206193, 2024).